FGF18 (fibroblast growth factor 18)
Diseases named in the same sentence as FGF18 in open-access papers (continued):
Sharing a sentence is not in itself a finding about the gene and the disease.
tumor (46 papers, 2010 to 2025). "Although the clinical relevance of FGF18 has been described in cancers, its underlying pathophysiological role in tumor progression remains elusive." (PMID 30082912, 2019). "Among the genes exhibiting altered expression levels, aqp1, map3k5, and fgf18 are highly expressed in tumor-associated blood vessels in several human tumors." (PMID 23929008, 2014). "Indeed, the overexpression of RPS15A in HCC is linked to an increase in fibroblast growth factor 18 (FGF18) expression following the stimulation of Wnt/β-catenin pathway which induces tumor angiogenesis." (PMID 34873618, 2021). "RPS15A promotes tumor angiogenesis via enhancing Wnt/β-catenin-induced fibroblast growth factor 18 (FGF18) expression through the Wnt/β-catenin pathway in HCC." (PMID 40521004, 2025). "FGF18 overexpression promotes tumor progression by enhancing tumor cell migration, invasion, and tumorigenicity." (PMID 40330466, 2025). "Analysis of signaling pathways by GSEA and gene expression analysis revealed that AZD4547-resistant tumor cells had enhanced c-Met signaling and higher FGF18 and FGF19 mRNA expression compared with AZD4547-sensitive cells." (PMID 38273381, 2024). "In tumor cells, we also found that high baseline expression of specific genes, including PCNA, FGF11, FGF18, CD274 (PD-L1) and HLA-A, was associated with a favorable response." (PMID 38245530, 2024). "The expression of fibroblast growth factor 18 (FGF18) within the tumor microenvironment then ramps up after the activity of the β-catenin and T cell factor/lymphoid enhancer-binding factor (Tcf/Lef) up-regulated." (PMID 39487553, 2024). "FGF18 has been described to be involved in para- and autocrine stimulation of tumour cells promoting cell growth and survival in several human malignancies." (PMID 37370765, 2023). "Its role in PM tumor biology and the clinical significance of decreased plasma FGF18 in PM patients warrant further investigation." (PMID 37340889, 2023). "Of note, our analysis identified FGF18 to be expressed in both tumour cell subclusters, interacting with the FGFR1 and FGFR2 receptors of fibroblast subclusters." (PMID 37370765, 2023). "We performed univariate and multivariate survival analyses including age, sex, histologic subtype, FGF18 levels, tumor site, tumor stage, and type of treatment." (PMID 37340889, 2023). "Although only a few functions of FGF18 in tumors have been reported, FGF18 has become an essential regulatory factor in tumor progression and is involved in controlling various physiological processes of tumors in multiple systems." (PMID 37228502, 2023). "With respect to tumor biology, the effects of FGF18 reported in the literature are tissue‐type specific." (PMID 37340889, 2023). "High FGFR1 expression in tumor tissues is associated with less favorable tumor characteristics, and FGF ligand (FGF1, FGF11, FGF18) expression is associated with MBD." (PMID 37546410, 2023). "Conversely, overexpression of FGF18 reversed the attenuated ability in tumor growth and metastasis mediated by downregulating HDAC7." (PMID 35277183, 2022). "The elevated FGF18 expression was also positively correlated to larger tumor size, T stage, lymphatic invasion, distant metastasis, TNM stages, and tumor differentiation." (PMID 35277183, 2022). "Similar to other FGFs, FGF18 also prefers to induce the formation of new blood vessels in HCC via directly or indirectly regulating VEGF of tumor cells and surrounding tissue cells of the tumor microenvironment." (PMID 33935756, 2021). "FGF18 plays a key role in regulating the biological activity of tumor cells and immediately surrounding tissue cells of the tumor microenvironment via multiple signaling pathways." (PMID 33935756, 2021). "In paired ccRCC neoplastic tissue, the ccRCC tumor tissue showed relatively low FGF18 immunoreactivity." (PMID 33117668, 2020).
tumor (continued). "As for tumor grade, high FGF18 expression was noted in 40 of 72 ccRCC T1 cases (55%) and in 3 of 10 ccRCC T2 cases (30%), which indicates that high ccRCC tumor grades correlate with low FGF18 expression (p = 0.045 < 0.05)." (PMID 33117668, 2020). "Further protein analysis of FGF18 overexpressed 786-O xenograft tumor compared to NC 786-O xenograft tumor also indicated elevated E-cadherin expression, decreased N-cadherin, Vimentin, and EMT related transcription factors." (PMID 33117668, 2020). "There is a recently published paper in GC delineating that miR-590-5p functions as a tumor suppressor by targeting FGF18." (PMID 32066878, 2020). "Fibroblast growth factor 18 was thought to be a tumor promotor and highly expressed in tumor tissue compared to paired normal tissue in various tumor types." (PMID 33117668, 2020). "Meanwhile, treating GC cells with human recombinant FGF18 or FGF18-conditioned medium accelerated tumor growth through activation of ERK-MAPK signaling." (PMID 30082912, 2019). "FGF18 plays a distinctive role in modulating the activity of both tumor cells and tumor microenvironment." (PMID 30082912, 2019). "Knocking down FGF18 inhibited tumor formation abilities, induced G1 phase cell cycle arrest and enhanced anti-cancer drug sensitivity." (PMID 30082912, 2019). "Their expressions showed a negative correlation in primary GC samples and more importantly, re-overexpression of FGF18 partly abolished the tumor-suppressive effect of miR-590-5p." (PMID 30082912, 2019). "Nevertheless, FGF18 protein levels correlated with disease status in our study and increased with tumour progression." (PMID 31336942, 2019). "For the first time, our study delineates that miR-590-5p functions as a tumor suppressor by targeting FGF18, which broadens our knowledge regarding the target pool of this miRNA in gastric tumorigenesis." (PMID 30082912, 2019). "Here, we provide the first evidence that FGF18 is an oncogenic factor in GC and negatively regulated by tumor suppressor miRNA, miR-590-5p." (PMID 30082912, 2019). "In vivo, re-overexpression of FGF18 significantly accelerated the tumor formation compared with the miR-590-5p-treated group." (PMID 30082912, 2019). "Given that FOS and FGF18 are involved in tumor growth, and invasion as well as PFDA stimulates cell growth and, the microarray data seemed to imply us that PFDA were involved in the processes of tumorigenesis." (PMID 28881615, 2017). "For example, Sonvillaet al. showed that FGF18 was progressively enhanced during colon carcinogenesis reaching very high levels in carcinomas and affecting both tumor cells and the tumor microenvironment in a pro-tumorigenic and pro-metastatic way." (PMID 25473897, 2015). "They further found that H19 was associated with angiopoietin (ANG) and fibroblast growth factor-18 (FGF-18), whose functions are involved in tumor growth and proliferation." (PMID 24063685, 2013). "Accordingly, we have recently demonstrated strong autocrine effects of FGF18 on tumour cell growth and survival." (PMID 20234367, 2010). "Although transfection of WT3c conferred sensitivity to FGF18-induced tumour cell migration, the dominant-negative KD3 virus reduced cell migration in both SW480 and Caco2 cells, but still permitted migration induced by 10% FCS." (PMID 20234367, 2010). "In the K562 cell line, the knockout of the active region of a SS (or referred to as an H3K27me3-rich region) results in the upregulation of the target genes, including FGF18, a gene involved in cell differentiation and cell migration, and subsequently inhibits tumor growth 24,25." (PMID 40631184, 2025). "In the K562 cell line, the knockout of the active region of a SS (or referring to as an H3K27me3-rich region) results in the upregulation of the target genes, including FGF18, a gene involved in cell differentiation and cell migration, and subsequently inhibits tumor growth." (PMID 40998810, 2025).
tumor (continued). "In addition, the continuous discovery of FGF18 in different organs or systems is of great significance in guiding tumor progression, which indicates that FGF18 can be used as an oncogene reference for the progression of multiple systemic tumors." (PMID 37228502, 2023). "Whether the net effect of these activities of FGF18 in vitro would favor or impair tumor progression in vivo remains unclear at present." (PMID 37340889, 2023). "In addition, ERK-MAPK signaling was also activated and accelerated tumor tissue growth, ultimately confirming FGF18 as a direct target of tumor suppressor miR-590-5p in inhibiting GC cell growth." (PMID 37228502, 2023). "In the in vivo experiment, subcutaneous injection of FGF18 knockdown or overexpression MDA-MB-231 cells into nude mice showed that the tumor size of FGF18 overexpression xenograft model was significantly larger than that of the control or FGF18 knockdown group." (PMID 37228502, 2023). "PAX8 may mediate some tumour-promoting effects through FOXM1 and tumour invasiveness through upregulation of FGF18." (PMID 36804485, 2023). "FGF18 with tumor type,phenotype or significance and functions in tumors." (PMID 37228502, 2023). "However, how FGF18 specifically directs tumor progression in embryonic and infantile tumors remains to be explored." (PMID 37228502, 2023). "Furthermore, the in vivo assay indicated that FGF18 overexpression significantly increased subcutaneous tumor weight in the A549 shHDAC7 group." (PMID 35277183, 2022). "FGF18 overexpression in 786-O significantly suppressed tumor volume and tumor weight (p < 0.05)." (PMID 33117668, 2020). "Furthermore, FGF18 expression significantly decreased with increasing tumor size (P = 0.011 < 0.05), as high FGF18 expression was noted in 22 of 49 ccRCC tumor size >3 cm (45%) cases and 21 of 33 ccRCC tumor size ≤3 cm (64%) cases." (PMID 33117668, 2020). "FGF18 was further confirmed to be a direct target of tumor suppressor, miR-590-5p." (PMID 30082912, 2019). "FGF18 knockdown exerts tumor suppressive effect on GC cells both in vitro and in vivo." (PMID 30082912, 2019). "Therefore, current research focuses on the exploration of oncogenes, such as the activation of proto-oncogenes and the inactivation of tumor suppressor genes, among which many cytokines, including fibroblast growth factor 18, are believed to be involved in the occurrence and development of tumors." (PMID 37228502, 2023). "However, FGF18-mediated interactions also originated in both tumour cell subclusters." (PMID 37370765, 2023). "Moreover, FGF18 silencing could dramatically attenuate subcutaneous tumor growth in the Calu-1 HDAC7 overexpression group." (PMID 35277183, 2022). "The administration of FGF8, FGF17, or FGF18 could resist apoptosis and enhance the survival of serum-starved tumor cells, including HCC-1.2, HepG2, and Hep3B cells, the mechanism studies have found that these effects were mediated by ERK and AKT/mTOR signaling pathways." (PMID 33935756, 2021). "Investigating these classical markers in our data, we did observe a statistically significant increase of TNF (TNF‐α) in G1 tumors, FGF14 in G2 tumors, and FGF8, FGF18, and PDGFA in G3 tumor in comparison to pancreatic islet cells." (PMID 39245631, 2025). "In patient samples, FGF18 overexpression correlates with increased microvessel density and TAM infiltration, confirming its involvement in driving tumor progression." (PMID 40330466, 2025). "We found that exposure to FGF2, FGF18, HBEGF, IGF1, PDGF-BB, and TGFα significantly (p < 0.0001) increased MCL1 expression in tumor cells (by at least 1.2-fold and up to 2-fold) and treatment with the MEKi reduced this response." (PMID 37676378, 2024). "The probability of interaction between tumor cells and fibroblast receptor-ligand pairs was higher than that of thyroid cells, especially in TGFB1/ACVR1/TGFBR1, FGF18/FGFR1, BTC/EGFR, BMP8A/BMPR1A/BMPR2, and BMP8A/BMPR1A/BMPR2." (PMID 37733241, 2023).
tumor (continued). "Thus, FGF18 may play an important role in the progression of tumor metastasis in PCC or PGL." (PMID 37228502, 2023). "The elevated expression of HDAC7 or FGF18 was positively correlated with poor prognosis, tumor–node–metastasis (TNM) stage, and tumor differentiation of NSCLC patients." (PMID 35277183, 2022). "Tumor cells expressed relatively high levels of EGFR, FGFR1, and FGFR2, while their corresponding ligands, such as COPA, GRN, HBEGF, FGF2, FGF7, and FGF18, were widely expressed in fibroblast cells." (PMID 34459128, 2021). "The overexpression FGF7, FGF9, FGF14, FGF18 and IGF1 genes was found significant in early tumor grades." (PMID 34061869, 2021). "Consistently, FGF18 expression and secretion are upregulated in a high-RPS15 A-expression HCC tumor microenvironment; FGF18 interacts with FGFR3 and contributes to angiogenesis by inducing the Wnt/β-catenin signaling pathway in endothelial cells." (PMID 33935756, 2021). "The results indicate that the mean HSCORES of FGF18, IL23A, and LIF in tumor tissues were significantly higher than those in normal tissues (p < 0.05), while the opposite trend was observed for SLIT2." (PMID 34017356, 2021). "Correlation of clinicopathological parameters and expression of FGF8, FGF18, and FGFR4 in the tumor tissue revealed significant correlations of the FGF8 protein level with tumor size ((y)pT), UICC stage, and Mandard regression grade." (PMID 31527546, 2019). "First, we measured the most widely used tumour markers, CA125 and HE4, to compare against the newly suggested biomarker, FGF18, in terms of sensitivity and specificity." (PMID 31336942, 2019). "In the present study, the expression patterns of a number of tumor-related classical genes (eg, VEGF, PGF, FGF18, AKT, E2F1, ATF5) within our microarray dataset were detected as predicted." (PMID 22962576, 2012). "Notably, several genes involved in cell cycle regulation (CCND2, CDKN2A/C), tumor microenvironment (COL3A1, COL1A1), and growth factor signaling (FGF18, ERBB2) showed significant upregulation with fold changes ranging from 1.5 to 2.0." (PMID 41419500, 2025). "In addition, at the protein level, FGF18, IL23A, LIF, and VGF stained more deeply in tumor tissues than in normal tissues, while CCL28 and SLIT2 were only deeply stained in normal intestinal mucosal tissues according to the Human Protein Atlas." (PMID 34017356, 2021). "We further validated higher FGF18 expression in normal renal tissue than paired ccRCC tumor tissues in five paired non-neoplastic and neoplastic tissues." (PMID 33117668, 2020). "Besides FGF8, FGF18, and FGFR4 the factors age, gender, tumor differentiation, UICC stage, lymph node ratio, adjuvant treatment, and Mandard regression grade (in neoadjuvantly treated patients only) were included." (PMID 31527546, 2019). "Furthermore, this is the first study comparing the expression of FGF8, FGF18, and FGFR4 in tumor tissue available before and after neoadjuvant treatment." (PMID 31527546, 2019). "Together, these results indicate that autocrine stimulation by FGF18 is one, but not the only, mechanism inducing tumour cell migration." (PMID 20234367, 2010). "In addition, the mRNA levels of tumor migration factors TGF-β, MMP-9 and MMP-2 as well as epithelial-mesenchymal transition (EMT) markers N-cadherin, vimentin, Snail-1, Snail-2 and TIMP-1 were also significantly up-regulated by FGF18 stimulation." (PMID 37228502, 2023). "Therefore, a TCGA analysis and immunohistochemistry, including tumor tissue from patients before and after neoadjuvant treatment, was performed to investigate the prognostic role of expression of FGF8, FGF18, and FGFR4 in adenocarcinomas of the esophago-gastric junction." (PMID 31527546, 2019). "However, FGF18 levels raised according to tumour stage (p = 0.0054) but were not correlated with any other clinical parameters like pre- and postmenopausal status, age, or tumour burden (data not shown)." (PMID 31336942, 2019).
cancer (24 papers, 2015 to 2025). A tumor composed of atypical neoplastic, often pleomorphic cells that invade other tissues. "We identified 30 cancer-specific normal-invariant genes, including Zic family members (ZIC1, ZIC4, and ZIC5), DPPA2, PRSS56, ELF5, and FGF18, most of which were cancer-associated genes." (PMID 39969322, 2024). "FGF18 is a potent mitogen for a variety of cells and plays an important role in directing cancers in organs or systems such as digestion and reproduction." (PMID 37228502, 2023). "The high FGF18 mRNA expression in PM cell lines as compared with cell lines from other cancer types suggested a potentially important role of FGF18 in PM, and therefore we next retrieved FGF18 gene expression data from the TGCA dataset of PM patients (n = 85)." (PMID 37340889, 2023). "The expression of Fgf18 is elevated in various human cancers, and its expression correlates with poor prognosis." (PMID 37813881, 2023). "With regard to malignant diseases, FGF18 has been shown to be overexpressed in several cancer types including hepatocellular, ovarian, and colorectal cancers." (PMID 37340889, 2023). "Altered FGF18 expression has been reported in a number of different cancer types and its presence has been connected to both pro‐ and antitumorigenic activities." (PMID 37340889, 2023). "In this study, we determined the differential expression of FGF18 in several cancer types in TGCA databases." (PMID 33117668, 2020). "We began to validate the FGF18 expression in paired normal and cancer tissues of 82 ccRCC patients enrolled between 2008 and 2014 in Huashan Hospital with tissue microarray." (PMID 33117668, 2020). "The important role of the overexpression of FGF18 has been identified in the progression of several types of cancers." (PMID 33117668, 2020). "In a few studies, particularly, the involvement of FGF18 has been identified under the context of cancer development." (PMID 30082912, 2019). "In summary, FGF8 and FGF18 are promising candidates for prognostic factors in adenocarcinomas of the esophago-gastric junction and new potential targets for new anti-cancer therapies." (PMID 31527546, 2019). "After demonstrating the tumor specific activity of FGF18 promoter, this was used in a new plasmid to deliver TK gene to cancer cells." (PMID 26648599, 2015). "Therefore, FGF18 has a significant relevance in OC cancer stem cell properties, and the pathways through which FGF18 mediates OC progression are very rich, and there are many more sites that still need to be explored." (PMID 37228502, 2023). "High gene expression of FGF18 was confirmed in the current study in PM cell lines compared with most cell lines from other malignancies and is in line with the TCGA gene expression comparison across multiple cancer types." (PMID 37340889, 2023). "Enriched pathways for upregulated miRNAs included: “Chemical carcinogenesis–receptor activation” (p-value = 0.018) associated with ESR1, FGF18, JAG1, KPNA6, PPARA genes; the pathway “Proteoglycans in cancer” (p-value = 0.089) associated with genes ESR1, FRS2, HIF1A, PDCD4." (PMID 36359024, 2022). "When deregulated, FGF18 promotes cancer growth, angiogenesis, and metastasis[45 ▶]." (PMID 32429632, 2020). "FGF18 overexpression tends to reduce the cancer cell colony in the HE staining of lung metastasis." (PMID 33117668, 2020). "Other hypermethylated age DMR genes from our data set classified two pathways relevant for growth and development (DCP1B, IGF1R, and FGF18) and cancer progression (TIAM1)—biological processes which has been also mentioned in the literature as epigenetic hallmarks of aging." (PMID 31281827, 2019). "To date, the exact molecular mechanism of FGF18 in cancer remains unclear." (PMID 37228502, 2023).